INS (insulin)
Diseases named in the same sentence as INS in open-access papers (continued):
Sharing a sentence is not in itself a finding about the gene and the disease.
type 2 diabetes (continued). "A possible explanation for this is that if a type 2 diabetes patient consumed excessive amounts of glucose (especially after a big meal), the insulin secreted by the pancreas was insufficient to transport glucose from the bloodstream into cells." (PMID 31909064, 2019). "Age-standardized and calendar year–standardized survival were lower in the type 2 diabetes group and lowest in the type 2 diabetes group prescribed insulin only." (PMID 31790564, 2019). "More research is needed to study the potential use of CTRPs known to improve insulin sensitivity and glucose tolerance in patients with type 2 diabetes." (PMID 30915034, 2019). "Skeletal muscle tissue is a main target of insulin-mediated glucose uptake, and skeletal muscle insulin resistance is a central step in type 2 diabetes disease progression." (PMID 31160616, 2019). "In type 2 diabetes, the basal insulin secretion is impaired, and FFA and the fasting glucagon levels are high." (PMID 30871141, 2019). "Chrebpb expression in human adipose tissue predicts insulin sensitivity, and its induction has been highlighted as an effective strategy for preventing and treating obesity-related metabolic dysfunction and type 2 diabetes." (PMID 31480627, 2019). "On the other hand, Mackenzie and colleagues showed that acute hypoxic exposure increased insulin sensitivity in individuals with type 2 diabetes." (PMID 31455007, 2019). "Widespread use of flash BG monitoring, which can replace a finger-stick glucometer even for insulin-treated type-2 diabetes patients." (PMID 31694629, 2019). "CTRP3 is lower in patients with type 2 diabetes and its levels are inversely proportional to blood glucose and insulin." (PMID 30915034, 2019). "In conclusion they stated that the advanced carbohydrate counting and insulin bolus calculation is an efficient, low cost tool to reduce HbA1c in people with type 2 diabetes on the basal-bolus insulin regimen." (PMID 30871141, 2019). "Bariatric/metabolic surgery procedures that reduce caloric intake, including SG, have shown high rates of remission of type 2 diabetes mostly due to the improvement of insulin sensitivity." (PMID 31754142, 2019). "Type 2 diabetes (T2D) is a metabolic disease characterized by hyperglycemia resulting from a resistance to insulin or a relative insulin insufficiency that can induce cardiovascular disease and lead to cardiovascular deterioration." (PMID 30097811, 2019). "Defects in the production or function of insulin can lead to type 1 or type 2 diabetes, which affect millions of people worldwide." (PMID 30747103, 2019). "In our study, decreased glucagon levels, and increased insulin levels were observed in type 2 diabetes group." (PMID 30674322, 2019). "Damage to insulin signaling in the brain has been suggested to be related to neurodegenerative disease, and some patients with type-II diabetes have exhibited impaired cognitive functions." (PMID 31311133, 2019). "Ser/Thr kinases such as JNK and IKK-b are two important factors that affect insulin signaling, further indicating that inflammatory tracks in bodily tissues can foster the inception of Type II diabetes." (PMID 31510091, 2019). "Total alkaloids of RC alleviated cognitive impairment in type 2 diabetic rats by reducing Aβ deposition and enhancing insulin signaling." (PMID 31396083, 2019). "Type 2 diabetes (T2D) develops after years of prediabetes during which high glucose (glucotoxicity) impairs insulin secretion." (PMID 30293774, 2019). "The latest clinical practice guideline “Optimal Use Recommendations for second- and third-line therapy for patients with type 2 diabetes” has recommended that DPP4i be used when patients are unable to use insulin as the third-line medication." (PMID 31877127, 2019). "The present study aimed to investigate the effect of M. quadrangula hydroethanolic extract on glucose tolerance, insulin sensitivity, glucose metabolizing enzymes, lipid profile, and adiponectin expression in type 2 diabetic rats." (PMID 30915195, 2019).
type 2 diabetes (continued). "The aim of this study was to assess the prevalence of type 2 diabetes and other types of impaired glucose metabolism in bipolar patients along with the evaluation of TyG index as a method of insulin sensitivity assessment." (PMID 30934836, 2019). "In our study short acting inhaled insulin Exubera® decreased HbA1c, fasting and post prandial blood glucose significantly in Type 2 diabetic patients over a period of 16 weeks." (PMID 31470605, 2019). "The most important known biological role of adiponectin is the regulation of insulin sensitivity in muscle cells, which makes it a central player in type 2 diabetes mellitus (T2DM) and metabolic syndrome." (PMID 31121868, 2019). "Analyse the effects of professional flash glucose monitoring system (FreeStyle Libre ProTM) on glycaemic control in insulin-treated type 2 diabetes." (PMID 31271312, 2019). "Type 2 diabetes is the insulin-dependent type and patients must be treated with insulin permanently." (PMID 30823412, 2019). "In the present study, we analyzed 13 type 1 diabetes susceptible SNPs, and compared them with those in controls and patients with type 2 diabetes clarify the genetic background of insulin‐triggered type 1 diabetes patients." (PMID 30970177, 2019). "Type 2 diabetes (known as non-insulin-dependent) results from the body’s inability to respond properly to the actions of insulin produced by the pancreas." (PMID 31266160, 2019). "Only mild non medicated type 2 diabetes is allowed among blood donors and we therefore repeated our main analyses of metS and insulin resistance excluding the two patients with BD with comorbid type 2 diabetes." (PMID 30937579, 2019). "It is well established that the protein tyrosine phosphatase PTPN1 directly regulates the insulin and the leptin signaling pathway, making it a promising therapeutic target for type II diabetes and obesity." (PMID 31527306, 2019). "Obese dogs often become insulin-resistant, but seldom become hyperglycaemic or develop type 2 diabetes in the same way as humans do." (PMID 30808390, 2019). "Based on the data obtained from animal studies, adults with type 2 diabetes, and women with gestational diabetes, it seems that adropin, afamin, and neudesin play a major role in the regulation of glucose metabolism and insulin sensitivity." (PMID 31781629, 2019). "For people with type 2 diabetes managed with medications other than insulin or sulphonylureas (or with lifestyle alone), ongoing pre-exercise glucose testing is not generally necessary due to the low risk of hypoglycaemia." (PMID 31161377, 2019). "HIIT elicited a significant reduction in BMI, body fat, HbA1c, fasting insulin, and VO2peak in patients with type 2 diabetes." (PMID 30097811, 2019). "Exercise is known to improve hyperglycemia and elevated levels of insulin, which are characteristic of patients with type 2 diabetes and have been shown to impair the production and availability of nitric oxide." (PMID 30885194, 2019). "In the current study, we developed resveratrol (RES)-loaded solid lipid nanoparticle (SLN-RES) in order to improve insulin resistance through the upregulation of SNARE protein complex in rats with type 2 diabetes." (PMID 31290033, 2019). "Type 2 diabetes is characterized by increased blood glucose, resistance to insulin action, and beta cell failure." (PMID 31652915, 2019). "We should emphasize the compensatory role of β-cells in the initial phases of type 2 diabetes when increased β-cell biogenesis, and hence β-cell mass, elevates insulin gene expression attempting to compensate the insufficient insulin regulation." (PMID 30450940, 2019). "Meanwhile, it functioned as a candidate gene for type 2 diabetes (T2D) by interacting with insulin signaling pathway." (PMID 31138106, 2019). "It exhibits insulin-independent antidiabetic effects in multiple animal models of type I and type II diabetes and antisteatotic effects in fatty liver models." (PMID 31092829, 2019).
type 2 diabetes (continued). "Empagliflozin, a sodium-glucose cotransporter 2 (SGLT2) inhibitor has recently been reported to improve glycaemic control in patients with type 2 diabetes in an insulin-independent manner." (PMID 30710997, 2019). "Protein tyrosine phosphatase 1B (PTP1B) plays a specific role as a negative regulator of insulin signaling pathways and is a validated therapeutic target for Type 2 diabetes." (PMID 31395821, 2019). "This study identifies the direct cost and economic burden of hypoglycemia for patients with type II diabetes mellitus on insulin in Malaysia." (PMID 31652253, 2019). "Obesity directly affects insulin function, which causes glucose to enter the cell membrane for energy metabolism, resulting in insulin resistance and type 2 diabetes." (PMID 31109115, 2019). "The untreated db/db mice showed typical type 2 diabetes characteristics, such as elevated levels of insulin and blood lipid, indicating the abnormal metabolisms of lipid as well as insulin resistance." (PMID 31215434, 2019). "The glucose target for the start of exercise for a person with type 2 diabetes treated with Insulin and/or Sulphonylureas is between 5.5 and 15.0 mmol/L." (PMID 31161377, 2019). "The metabolism of branched-chain amino acids plays other critical roles in human health, including ammonia detoxification, protein biosynthesis and insulin sensitivity while serving as predictive biomarkers of type 2 diabetes." (PMID 31600930, 2019). "Our findings can inform future trials aiming to manipulate gut microbiome to improve insulin sensitivity and secretion and prevent type 2 diabetes." (PMID 30987356, 2019). "This work concentrates on the daily life support of type 1 and type 2 diabetes outpatients treated with subcutaneous insulin injections." (PMID 30774850, 2019). "The aim of this pilot study was to determine the effect of a single dose of a novel delayed-release nutrient (DRN) on glucose, GLP-1, c-peptide, insulin, and appetite in adults with obesity and type 2 diabetes." (PMID 31308360, 2019). "Insulin therapy in people with type 2 diabetes is significantly different from that used to treat people with type 1 diabetes." (PMID 30871141, 2019). "The most common form of this disease, type 2 diabetes, develops when pancreatic β-cells are unable to secrete an adequate amount of insulin to compensate for peripheral insulin resistance." (PMID 31498851, 2019). "This is because at the time of the protocol writing, local and international guidelines were recommending the initiation of insulin therapy in type 2 diabetes when HbA1c levels were between 8.5 and 10%." (PMID 30732583, 2019). "Reduced insulin sensitivity in skeletal muscle is the main defect that links obesity and type 2 diabetes." (PMID 31013777, 2019). "Studies in people with high adiposity, impaired glucose levels, and Type 2 diabetes have reported greater attenuation of postprandial insulin and glucose in response to breaking up sitting compared with studies in “healthy” samples." (PMID 31244676, 2019). "The disrupted coordination of glucagon and insulin secretion observed in type 2 diabetes is characterized by impaired and delayed insulin secretion as well as basal hyperglucagonemia and non-suppressed glucagon secretion in response to glucose." (PMID 30849121, 2019). "EMP is a relatively new FDA-approved agent for the management of type 2 diabetes, and recent findings have proved its efficacy in the management of type 1 diabetes as an adjunctive therapeutic agent added to insulin." (PMID 31168342, 2019). "While the last is a commercial kit, the FLI and the NAFLD liver fat score are based on serum triglycerides (TG), gamma-glutamyl transferase, insulin, aminotransferases, waist circumference, BMI and presence of metabolic syndrome or type 2 diabetes." (PMID 31010049, 2019).
type 2 diabetes (continued). "To summarise, use of professional flash technology in insulin-treated type 2 diabetes managed within primary and secondary care sites was associated with a significant reduction in HbA1c level and improved satisfaction with treatment." (PMID 31271312, 2019). "We found that the enriched terms were more specific and striking with T2D when considering only the top100 prioritized housekeeping genes, such as type II diabetes mellitus, insulin signaling pathway, and glucose metabolic process." (PMID 30972105, 2019). "Thiazolidinediones, such as rosiglitazone, metformin, and glyburide, have been used as insulin-sensitizing drugs for the treatment of type 2 diabetes." (PMID 30939853, 2019). "Glitazones are the new categories of insulin sensitizers, which are currently preferred over other hypoglycemic agents for Type 2 diabetes therapy, because of their positive effects on glucose level, insulin sensitivity, and the cardiometabolic profile." (PMID 31340601, 2019). "Type 2 diabetes mellitus (T2DM) is a metabolic disorder characterized by high levels of blood glucose resulting from altered insulin secretion or action." (PMID 31892956, 2019). "Recent studies have also suggested that green tea and yellow tea increase insulin sensitivity and glucose metabolism, preventing progress of type 2 diabetes." (PMID 31109113, 2019). "This malady is due to either insufficient insulin production by the pancreas or by failure of the body cells to respond normally to the produced insulin (type 1 or type 2 diabetes, respectively)." (PMID 31489927, 2019). "Forty-six diabetic patients routinely took insulin (all patients with type 1 diabetes and 22 patients with type 2 diabetes)." (PMID 30606177, 2019). "The counterbalance between insulin secretion and insulin resistance is critical for type 2 diabetes pathogenesis." (PMID 31183505, 2019). "Here, we describe a patient with type 2 diabetes with an insulin allergy in which severe DKA resolved after the initiation of continuous intravenous (IV) recombinant human insulin infusion in combination with haemodiafiltration." (PMID 31711488, 2019). "This is keeping with previous large-scale metabolic profiling studies and consistent with the pathophysiology of type 2 diabetes, where insulin sensitivity gradually declines years before clinical disease onset." (PMID 31584131, 2019). "This multicenter, randomized controlled trial evaluated efficacy, safety, and self-reported outcomes in adults with type 2 diabetes, inadequately controlled on basal insulin, initiating and managing mealtime insulin with a wearable patch versus an insulin pen." (PMID 31025878, 2019). "Type 1 diabetes is an autoimmune disease that arises when T-cell mediated destruction of insulin-producing β cells occurs, whereas type 2 diabetes is a chronic disease which commences when insulin resistance develops in the body." (PMID 32010189, 2019). "Then, the effect of oral treatment of SLN-RES on the fasting blood sugar (FBS), insulin, and oxidative stress parameters was evaluated in rats with type 2 diabetes." (PMID 31290033, 2019). "In conclusion, P. pavonia-derived terpenes attenuated hyperglycemia, dyslipidemia, oxidative stress, and inflammation, and improved insulin sensitivity and carbohydrate metabolism in type 2 diabetic rats." (PMID 31887984, 2019). "Hypoglycemia is a common treatment-related event among patients with type 1 diabetes (T1D) or type 2 diabetes (T2D) treated with insulin and is often a key barrier to obtaining good glycemic control." (PMID 31397845, 2019). "GLP-1 is an incretin hormone that stimulates insulin secretion and forms the basis of a drug class for type 2 diabetes treatment." (PMID 30823876, 2019). "In this respect, previous studies found the beneficial effects of phlebotomy and blood donation in patients with type 2 diabetes, demonstrating that iron reduction by phlebotomy improved insulin sensitivity." (PMID 31470879, 2019).
type 2 diabetes (continued). "Long-term daily consumption leads to an increase in weight and a decrease in insulin sensitivity, favoring the development of MetS and type 2 diabetes, both in children and in adults." (PMID 31450565, 2019). "Rosiglitazone and other synthetic ligands of PPARγ have been used as insulin sensitizers for the treatment of type 2 diabetes." (PMID 30845932, 2019). "In parallel with these findings, insulin-sensitising drugs, which are commonly used in humans with type 2 diabetes, are known to upregulate AMPK in liver, adipose tissue and skeletal muscle." (PMID 31691163, 2019). "In 2016, a short message service text messaging intervention to titrate insulin in patients with uncontrolled type 2 diabetes was implemented at two health care facilities in New York City." (PMID 31368439, 2019). "Another regulator of type 2 diabetes is miR-143, that acts by phosphorylation of insulin pathways in peripheral tissues." (PMID 31817583, 2019). "Mounting evidence has suggested that obesity-associated inflammation, so-called meta-inflammation, triggers glucose intolerance and type 2 diabetes by interrupting insulin signaling in insulin-target tissues." (PMID 31727092, 2019). "In conclusion, sotagliflozin seems to represent a promising treatment for both type 1 and type 2 diabetes, either alone or in combination with metformin or DPP-4 inhibitors in type 2 diabetes or, with an adequate insulin protocol, in type 1 diabetes." (PMID 30819210, 2019). "Strong associations have been reported between the type 2 diabetes risk allele and higher fasting glucose and higher 2-h glucose level during oral glucose tolerance test (OGTT) with lower 2-h insulin level and HOMA in adults." (PMID 32082357, 2019). "To determine if inactivation of PPP1R15A would have a net beneficial or detrimental effect in metabolic disease, we set out to model the later stages of type 2 diabetes wherein beta-cell mass falls in the face of sustained insulin resistance." (PMID 30814564, 2019). "OGTT and IPITT are used to assess glucose tolerance and insulin sensitivity, and to identify hyperglycemia and type 2 diabetes." (PMID 31323977, 2019). "Contrary to the limited amount of evidence in critically ill patients, in type 2 diabetes numerous epidemiological studies have showed a (dose-dependent) relation between insulin and adverse events (e.g., cardiovascular events, malignancies and mortality)." (PMID 30742240, 2019). "We present a case of a Hispanic female with type 2 diabetes phenotype who underwent bariatric surgery and post-operatively stopped her insulin therapy due to multiple reasons, including decreased oral intake and concern for hypoglycemia." (PMID 30697192, 2019). "Low glycemic index (GI) diets reduce postprandial glucose (PPG) by slowing digestion and the rate of nutrient influx from the gut and help to modulate insulin responses, thereby eliciting a beneficial effect in type 2 diabetes and other chronic maladies." (PMID 31737676, 2019). "Type 2 diabetes (T2D) largely affects older subjects and involves impaired insulin secretion and/or action." (PMID 30635569, 2019). "Although validation studies of surrogate indices in various populations are limited, insulin sensitivity/resistance assessed by these indices have been shown to be relevant in the prediction of type 2 diabetes or occurrence of cardiovascular diseases (CVD)." (PMID 30934836, 2019). "The base case ICER falls approximately below one-third the defined WTP threshold in Hong Kong making glargine U100 a highly cost-effective insulin option in patients with type 2 diabetes." (PMID 31303866, 2019). "Of the participants, 68/115 (59.1%) were Type 2 diabetics, 91/115 (79.1%) were insulin dependent, and 108/115 (93.9%) used a glucometer." (PMID 30990455, 2019). "Added insulin increased the epithelial cell layer tightness in normal glucose concentrations, and the effect was more evident in type 2 diabetics than in healthy control hiPSC-RPE cells." (PMID 31375001, 2019).